XRCC2 (X-ray repair cross complementing 2)
Diseases named in the same sentence as XRCC2 in open-access papers (continued):
Sharing a sentence is not in itself a finding about the gene and the disease.
lung carcinoma (8 papers, 2011 to 2024). "In contrast, no direct relation was observed between the occurrence of rs3218536 variant of the XRCC2 gene and the incidence of lung cancer or sporadic colorectal cancer." (PMID 26339569, 2015). "Considering the regulatory effect of XRCC2 on vimentin stability, we aimed to investigate the involvement of XRCC2 in lung cancer metastasis." (PMID 39090304, 2024). "Functional investigations through in vivo and in vitro experiments reveal the role of XRCC2 in promoting lung cancer migration and invasion." (PMID 39090304, 2024). "Our findings were consistent with previous reports that silencing XRCC2 expression using RNA interference technology similarly improved the radiosensitivity of human brain tumor and lung cancer cells." (PMID 24481064, 2014). "An investigation suggested that the abnormal upregulation of XRCC2 gene expression rendered lung cancer cells’ resistance to DNA damage induced by radiation, which resulted in tumors’ resistance to radiotherapy." (PMID 24481064, 2014). "Additionally, overexpression of XRCC2 reduced cell cycle arrest and enhanced the sensitivity to chemoradiotherapy in lung cancer cells." (PMID 39090304, 2024). "Previous studies found some potentially functional SNPs of HR genetic polymorphisms (e.g., RAD51-135 G>C, −172G>T, XRCC2 4234G>C, R188H, XRCC3 T241M and NBN E185Q) to be associated with various types of cancer risks, including cancers of the lung, breast, ovary, leukemia and head and neck." (PMID 21647442, 2011). "Our findings suggest a potential involvement of SNAP25-AS1, RP11-58O9.2, TENM4, XRCC2, LINC01164, VLDLR-AS1, RP11-14I17.2, and CDKN1A in the development of hypoxia-induced lung cancer." (PMID 39236027, 2024). "Co-expression network construct indicated that some of the mostly connected mRNAs and TFs were previously reported to be dysregulated in lung cancer, including SOX2, FOXF1, PTK2B, XRCC2, AML-1a (RUNX1), GATA-2 and MZF1." (PMID 26159226, 2015).
cervical carcinoma (7 papers, 2015 to 2024). A carcinoma arising from either the exocervical squamous epithelium or the endocervical glandular epithelium. "In conclusion, this study indicates an association of RAD51 rs1801320 and XRCC2 rs3218536 polymorphisms with cervical cancer development in the Bangladeshi population." (PMID 34319032, 2021). "Association of genotypes of CYP1A1 T>C rs4646903, CYP1A1 A>G rs1048943, CYP2E1 T>A rs6413432, RAD51 G>C rs1801320, XRCC1 G>A, rs25487 XRCC2 G>A rs3218536 and XRCC3 C>T rs861539 polymorphisms with clinical response of cervical cancer cases (n = 227)." (PMID 35996502, 2022). "Association of genotypes of CYP1A1 T>C rs4646903, CYP1A1 A>G rs1048943, CYP2E1 T>A rs6413432, RAD51 G>C rs1801320, XRCC1 G>A rs25487, XRCC2 G>A rs3218536 and XRCC3 C>T rs861539 polymorphisms and survival after treatment (CRT) for cervical cancer." (PMID 35996502, 2022). "Association of genotypes of CYP1A1 T>C rs4646903, CYP1A1 A>G rs1048943, CYP2E1 T>A rs6413432, RAD51 G>C rs1801320, XRCC1 G>A, rs25487 XRCC2 G>A rs3218536 and XRCC3 C>T rs861539 polymorphisms with vital status and recurrence of cervical cancer cases (n = 227)." (PMID 35996502, 2022). "Here, we hypothesized that both RAD51 rs1801320 and XRCC2 rs3218536 are associated with risk of cervical cancer development and performed this case-control study of in the population of Bangladesh to identify the association with the development of cervical cancer." (PMID 34319032, 2021). "Alterations in common DNA repair genes (RAD51 and XRCC2) may lead to cervical cancer (CC) development." (PMID 34319032, 2021). "The role of genetic polymorphisms in key DNA repair genes such as XRCC1, XRCC2, and XRCC3, along with their respective SNPs, has been extensively studied for their association with cancer risk across different types of cancers, such as lung, breast, and cervical cancer." (PMID 38983993, 2024).
pancreatic cancer (7 papers, 2009 to 2022). "In pancreatic cancer, the AA genotype of XRCC2 G>A rs3218536 was associated with a significantly shorter survival than the GG/GA genotype." (PMID 35996502, 2022).
glioma (6 papers, 2021 to 2024). A benign or malignant brain and spinal cord tumor that arises from glial cells (astrocytes, oligodendrocytes, ependymal cells). "As expected, the results showed that XRCC2 has a higher expression level in gliomas with higher malignancy and that the expression level of XRCC2 is lower in patients with IDH mutation and 1p/19q co-deletion than in the corresponding control group." (PMID 34051735, 2021). "We found that XRCC2 is an independent risk factor for poor prognosis in glioma patients and has a high diagnostic value for glioma prognosis." (PMID 34051735, 2021). "As we predicted, XRCC2 was an independent risk factor for poor prognosis in glioma, demonstrated by meta-analysis of multiple datasets." (PMID 34051735, 2021). "Cox and meta-analyses showed that XRCC2 is an independent risk factor for the poor prognosis of glioma." (PMID 34051735, 2021). "The expression of XRCC2 was reduced in gliomas with IDH mutation and 1p/19q co-deletion (P < 0.001)." (PMID 34051735, 2021). "Therefore, we have reason to believe that XRCC2, which is highly expressed in gliomas, is an independent risk factor affecting the prognosis of gliomas." (PMID 34051735, 2021). "To further clarify whether XRCC2 is an independent risk factor for the prognosis of glioma patients, we conducted univariate and multivariate analyses." (PMID 34051735, 2021). "Taken together, we believe that the overexpression of XRCC2 may be considered an independent risk factor of poor prognosis in glioma patients." (PMID 34051735, 2021). "Within subtypes of brain cancer, the top three mutation rates were MAD2L2/FANCV (21.49%) in meningioma, XRCC2/FANCU (17%) in rhabdoid tumors, and ATM (16%) in pediatric high-grade gliomas." (PMID 39421870, 2024). "XRCC2, a novel oncogene, is significantly overexpressed in glioma and can lead to poor prognosis in glioma patients." (PMID 36092717, 2022). "XRCC2 expression was also analysed in silico using multiple data sets in relation to the prognosis of glioma patients." (PMID 36293346, 2022). "The expression characteristics of XRCC2 in thousands of glioma samples from CGGA and TCGA databases were comprehensively analyzed." (PMID 34051735, 2021). "This is the first study to show that XRCC2, a novel oncogene, is significantly overexpressed in glioma and can lead to poor prognosis in glioma patients." (PMID 34051735, 2021). "Since IDH mutation and 1p/19q co-deletion are currently recognized as predictors of better prognosis in glioma patients, this result indirectly supports the adverse effect of XRCC2 on the prognosis of glioma." (PMID 34051735, 2021). "To understand the impact of XRCC2 on the prognosis of glioma, we first used Kaplan–Meier analysis to analyze the relationship between the expression level of XRCC2 and the prognosis of glioma patients based on three different data sets." (PMID 34051735, 2021). "To determine the effect of XRCC2 overexpression on the prognosis of glioma patients, we performed survival analysis on different data sets, and, as predicted, we found that overexpression of XRCC2 reduced patient survival." (PMID 34051735, 2021). "Wilcox or Kruskal test was used to analyze the expression pattern of XRCC2 in gliomas with different clinical and molecular features." (PMID 34051735, 2021). "Gene set enrichment analysis (GSEA) revealed the possible cellular mechanisms involved in XRCC2 in glioma." (PMID 34051735, 2021). "Based on the mutual validation of multiple public databases, we identified the possible XRCC2 signaling pathways involved in the malignant progression of glioma and screened four small-molecule drugs with potential clinical application value." (PMID 34051735, 2021). "Connectivity map (CMap) was used to screen small molecule drugs targeting XRCC2 and the expression levels of XRCC2 were verified in glioma cells and tissues by RT-qPCR and immunohistochemical staining." (PMID 34051735, 2021).
glioma (continued). "Subsequently, it lays the foundation for studying the relationship between XRCC2 and glioma histology." (PMID 34051735, 2021). "The effect of XRCC2 on the prognosis of glioma patients was explored by Kaplan–Meier and Cox regression." (PMID 34051735, 2021). "This study comprehensively analyzed the expression pattern of XRCC2 in glioma and found that overexpression of XRCC2 can reduce the survival rate of glioma patients." (PMID 34051735, 2021). "To elucidate the cellular mechanisms by which the overexpressed XRCC2 leads to tumoral progression in glioma, we used GSEA to analyze the data from the CGGA and TCGA databases." (PMID 34051735, 2021). "These signaling pathways targeted by XRCC2 indicate that XRCC2, as an oncogene, is involved in the occurrence and malignant progression of glioma through multiple pathways, ultimately affecting the prognosis of patients." (PMID 34051735, 2021). "This study pioneered in exploring the expression pattern of XRCC2 in glioma, clarifying that XRCC2 can act as an oncogene and reduce the survival rate of glioma patients." (PMID 34051735, 2021). "This study analyzed the expression pattern of XRCC2 in gliomas and its relationship with prognosis using multiple datasets." (PMID 34051735, 2021). "To identify small-molecule drugs that can be used to target XRCC2 against glioma, we explored four small-molecule compounds with potential clinical applications using CMap online tools based on the CGGA RNA-seq dataset: doxazosin, quinostatin, canavanine, and chrysin." (PMID 34051735, 2021). "Since XRCC2 was not involved in the malignant progression of glioma through a single cellular mechanism, we speculated that other genes co-express with XRCC2 in glioma." (PMID 34051735, 2021). "In order to reduce the harm caused by XRCC2 overexpression, based on the CGGA RNA-seq dataset we identified small molecules that target XRCC2 that have the potential clinical application of improving the status of glioma treatment and the prognosis of glioma patients." (PMID 34051735, 2021). "Our survival analysis showed that lower grade glioma patients with tumors expressing lower levels of XRCC2 prior to treatment have better outcomes on temozolomide, potentially because the function of XRCC2 counteracts the drug’s mechanism of action." (PMID 33654134, 2021). "Finally, doxazosin, quinostatin, canavanine, and chrysin were identified to exert anti-glioma effects by targeting XRCC2." (PMID 34051735, 2021). "As the occurrence of cancer is dependent on many factors, we used univariate and multivariate analyses to test whether this effect of XRCC2 on the prognosis of glioma is an independent factor." (PMID 34051735, 2021). "This study aimed to find out the role of XRCC2 in glioma and reveal in which glioma-specific biological processes is XRCC2 involved based on thousands of glioma samples, thereby, providing a new perspective in the treatment and prognostic evaluation of glioma." (PMID 34051735, 2021). "XRCC2 could serve as a new biomarker for glioma diagnosis, treatment, and prognosis evaluation, thus bringing new insight into the management of glioma." (PMID 34051735, 2021). "Since the results of this study suggest that overexpression of XRCC2 can lead to poor prognosis, we speculated that different clinical features of gliomas may predict differences in XRCC2 expression." (PMID 34051735, 2021). "XRCC2 has different expression levels in different grades of glioma." (PMID 34051735, 2021). "In addition, the samples were divided into high expression and low expression groups according to the average value of XRCC2 expression in the 23 glioma samples." (PMID 34051735, 2021). "Therefore, we analyzed the expression levels of XRCC2 in gliomas with different characteristics based on the three different data sets." (PMID 34051735, 2021).
glioma (continued). "This may be because the interaction between XRCC2 and histology reduces the effect of histology on the prognosis in multivariate analysis, which further reveals that XRCC2 can affect other factors to reduce the prognosis of glioma." (PMID 34051735, 2021). "Therefore, we believe that the four small molecule compounds identified by us may soon play an essential role in anti-glioma therapy targeting XRCC2." (PMID 34051735, 2021). "Therefore, we speculate that XRCC2 is involved in the malignant progression of glioma as an oncogene and, hence, its overexpression affects the prognosis of patients." (PMID 34051735, 2021). "Therefore, we speculated that the expression level of XRCC2 in glioma may also be correlated with multiple clinical and molecular characteristics associated with its prognosis." (PMID 34051735, 2021). "However, the role and expression pattern of XRCC2 in glioma have not been elucidated so far." (PMID 34051735, 2021).
rectal cancer (6 papers, 2015 to 2023). A primary or metastatic malignant neoplasm that affects the rectum. "In the paraffin specimens obtained from rectal cancer patients, positive XRCC2 expression was found to be associated with TNM stage (P = 0.024)." (PMID 26320178, 2015). "For example, silencing XRCC2 can block the cell cycle and increase the sensitivity of rectal cancer cells to radiotherapy, while the overexpression of XRCC2 in colon cancer promotes the proliferation of cancer cells." (PMID 34051735, 2021). "XRCC2 was found to increase locally advanced rectal cancer radioresistance by repairing DNA double-strand breaks and preventing cancer cell apoptosis." (PMID 31277598, 2019). "Here, XRCC2 expression was investigated as a predictor of preoperative radiotherapy (PRT) treatment response in locally advanced rectal cancer (LARC)." (PMID 26320178, 2015). "XRCC2 was found to be overexpressed in rectal cancer tissues resected from patients who underwent surgery without PRT." (PMID 26320178, 2015). "Positive XRCC2 staining was only detected in 57/100 (57%) primary rectal cancer tissues." (PMID 26320178, 2015). "In conclusion, the results of this study demonstrate that XRCC2 is upregulated in rectal cancer compared to adjacent normal rectal tissues and this may promote rectal cancer progression." (PMID 26320178, 2015). "Thus, XRCC2 appears to be an independent biomarker for predicting how well rectal cancer will respond to PRT." (PMID 26320178, 2015). "Therefore, to our knowledge, we have provided the first clinical evidence that XRCC2 may play an important role in the progression of rectal cancer." (PMID 26320178, 2015). "In subsequent Western blots, levels of XRCC2 protein were also higher in the rectal cancer samples than in the matched adjacent non-tumor tissues." (PMID 26320178, 2015). "Levels of XRCC2 mRNA were detected in 50 snap-frozen rectal cancer tissue samples and 50 matched, adjacent noncancerous tissue samples." (PMID 26320178, 2015). "In the present study, XRCC2 expression was detected in freshly frozen rectal cancer specimens, and both mRNA and protein levels of XRCC2 were found to be higher in rectal cancer tissues than in matched adjacent noncancerous tissues." (PMID 26320178, 2015).
colon carcinoma (5 papers, 2014 to 2022). "Evidence is yielded by this study that RAD51 and XRCC2 gene polymorphisms may be risk factors for colon cancer progress." (PMID 32458654, 2020). "Knockdown of XRCC2 in colon carcinoma cells decreased cell proliferation, increased apoptosis and lead to cell cycle arrest induced by irradiation." (PMID 31775835, 2019). "In the study, we adopted vector-based shRNA expression system to investigate the effect of XRCC2 silencing on sensitization to X-radiation in colon cancer in vitro and in vivo." (PMID 24481064, 2014). "In summary, knockdown of XRCC2 significantly sensitized colon tumor cells to radiation, as assayed in both in vitro cell culture and in vivo xenograft tumor models." (PMID 24481064, 2014). "To test this possibility, we studied the effect of XRCC2 suppression on radiosensitivity of colon cancer cells." (PMID 24481064, 2014). "Our data suggest that the suppression of XRCC2 expression rendered colon tumor cells more sensitive to radiation therapy in vitro and in vivo, implying XRCC2 as a promising therapeutic target for the treatment of radioresistant human colon cancer." (PMID 24481064, 2014). "Here, we investigated the effect of XRCC2 silencing on colon tumor cells’ growth and sensitivity to X-radiation in vitro and in vivo." (PMID 24481064, 2014). "Collectively, our experimental data suggest that knockdown of XRCC2 expression enhances colon tumor cells’ sensitivity to radiotherapy in vitro and in vivo." (PMID 24481064, 2014). "The results suggested that the knockdown of XRCC2 rendered colon tumor cells more sensitive to reradiation." (PMID 24481064, 2014). "As uncontrolled growth is one of important alteration in cancer cell phenotypes, we firstly examined the effect of XRCC2 knockdown on the growth of T84 colon tumor cells." (PMID 24481064, 2014). "Given the elevated level of XRCC2 protein in T84 colon cancer cell line, we selected T84 in subsequent experiment." (PMID 24481064, 2014). "In conclusion, knockdown of XRCC2 expression has radiosensitization effects on colon tumor cells in vitro and in vivo." (PMID 24481064, 2014). "Thus, we adopted shRNA-mediated XRCC2 silencing strategy to investigate the effect of XRCC2 silencing on cell growth and sensitization to X-radiation in colon cancer in vitro and in vivo." (PMID 24481064, 2014). "In addition, tumor xenograft studies showed XRCC2 silencing similarly inhibited tumor growth in vivo, suggesting XRCC2 as an important regulator of colon tumor cellular proliferation." (PMID 24481064, 2014). "The role of the DNA repair protein XRCC2 on colon cancer radioresistance remains poorly understood." (PMID 24481064, 2014). "The study suggest that XRCC2 might be a radiotherapy target in colon cancer, and that XRCC2 gene-specific therapy may be developed as an assistant method of enhancing the antitumor effect of traditional radiation treatment." (PMID 24481064, 2014). "However, there are no studies on XRCC2 expression in colon cancer and its association with sensitivity to IR." (PMID 24481064, 2014). "In the present study, we found that the expression of XRCC2 protein was elevated in colon cancer cells compared with normal cells." (PMID 24481064, 2014). "Until now, it is not yet known whether the level of XRCC2 expression can affect the sensitivity of radiotherapy for colon cancer and whether XRCC2 can predict the efficacy of colon cancer radiotherapy." (PMID 24481064, 2014).